TIGIT (T cell immunoreceptor with Ig and ITIM domains)
Diseases named in the same sentence as TIGIT in open-access papers (continued):
Sharing a sentence is not in itself a finding about the gene and the disease.
tumor (continued). "Together, these findings suggest that TIGIT expression is upregulated on both CD96+CD8+ T cells and CD226+CD8+ T cells within the tumour microenvironment of LUAD." (PMID 38279870, 2024). "Tumor-specific CD4 + T cells showed higher expression levels of chemokine CXCL13, immune regulators FOS and JUN, and exhaustion markers TIGIT." (PMID 39033098, 2024). "The extracted tumor tissue was confirmed as TNBC by HE staining, and it was found that tumor progression was significantly inhibited in mice treated with anti-TIGIT mAb." (PMID 38216949, 2024). "To summarize, we generated a novel trispecific antibody combining tumor targeting, CD16 engagement, and TIGIT checkpoint inhibition in one molecule." (PMID 38474651, 2024). "The results showed that TIGIT and NECTIN2 co-localized spatial in both types of tissues, reflecting that the tumor cells and immune cells communicated frequently through this receptor-ligand axis to create immune-suppressive environment." (PMID 39474422, 2024). "Despite activating receptors on the target enhance NK cell-mediated tumor lysis, expression of ligands on tumors to inhibitory NK receptors, such as NKG2A, TIGIT and LAG3, can induce NK cell exhaustion and suppress their anti-tumor function." (PMID 39415291, 2024). "Tregs, as one of the most important parts of immunosuppressive cells, can inhibit tumor-specific immune responses with the co-inhibitory molecules such as CTLA-4, TIGIT, LAG3, and CD28, and promote immune evasion, thus facilitating tumor cell proliferation." (PMID 38671348, 2024). "In the tumor microenvironment of patients with T-ALL/T-LBL, the immunosuppressive components TIGIT and CTLA4 show reduced expression." (PMID 38464517, 2024). "TIGIT functions as an immune checkpoint by interacting with its ligand, CD155, which is expressed on both tumor cells and immune cells." (PMID 39415846, 2024). "ZGGS15, a BsAb that blocks both LAG-3 and TIGIT, can potently inhibit LAG-3 and TIGIT receptors on immune cells by attaching to their specific binding ligands, MHC-II and PVR (CD155), on tumor cells." (PMID 38724599, 2024). "This Tri-NAb, targeting PDL1, 4-1BB, and NKG2A (or TIGIT) simultaneously, effectively binds to NK and CD8+ T cells, triggering their activation and proliferation, while facilitating their interaction with tumor cells, thereby inducing efficient tumor killing." (PMID 39043643, 2024). "It was found that CD226 was downregulated in TIGIT+CD8+ follicular lymphoma T cells compared with TIGIT−CD8+ cells, which further promoted the immune escape process of tumor cells." (PMID 38229100, 2024). "Overall, detailed characterization of the intra-tumor expression of CD226, CD155, TIGIT, CD112, and CD112R can provide critical insights into the tumor immune landscape, supporting patient selection for more effective, tailored immunotherapeutic strategies." (PMID 39684559, 2024). "Preclinical studies have demonstrated that antibodies blocking TIGIT plus PD-L1 or TIM-3 simultaneously can specifically enhance the effector function of CD8+ T-cells, leading to significant anti-tumour immune response." (PMID 38660136, 2024). "Increasing evidence has demonstrated that TIGIT was highly expressed on tumor-infiltrating NK cells in hematological malignancies, such as AML, resulting in tumor progression and poor outcomes." (PMID 38396050, 2024). "Coincidentally, they are both ligands for TIGIT, and the expression of PVR and NECTIN2 is strongly correlated with epithelial and endothelial cells, and are more expressed in tumor tissues than in normal tissues." (PMID 39120585, 2024). "TIGIT interacts with different ligands, including CD155 expressed on dendritic cells, thereby inhibiting tumor killing by NK cells and antigen presentation by dendritic cells, thus weakening the anti-tumor effect of T cells." (PMID 38404571, 2024).
tumor (continued). "NK/T cell subgroups in HNSCC group highly expressed marker genes of depleted T cells such as CTLA4, LAG3, TIGIT, HAVCR2, etc., indicating that tumor tissue was more sensitive to NK/T cells." (PMID 38582791, 2024). "In the past, TIGIT expressed on human NK cells was shown to bind to PVR and PVRL2 and inhibit tumor killing by NK cells." (PMID 39156900, 2024). "Dual PD-1/TIGIT blocking enhances in vitro expansion and function of tumor antigen-specific CD8+ T cells and promotes tumor rejection in mouse tumor models." (PMID 39845973, 2024). "TIGIT's ligands, CD155 and CD112, are expressed on tumor cells and APCs, further establishing its critical role in tumor immune responses." (PMID 38342925, 2024). "Most of the CD8+ T cells in the tumor were CD45RAloCD27hi and expressed PD-1, TIM-3, CTLA-4, LAG-3, TIGIT, and CD39." (PMID 39273452, 2024). "TIGIT is primarily expressed on the surface of T cells and NK cells, and CD155 on tumor cells is a high-affinity ligand for TIGIT." (PMID 39013849, 2024). "Tumor-promoting genes such as CD163 and CD209 were highly expressed in the myeloid cells, and depletion marker genes such as TIGIT, LAG3 were highly expressed in NK/T cells." (PMID 38582791, 2024). "FCM demonstrated that there were more CD155 tumour cells and CD4 + CD25 + Treg cells showed increased TIGIT levels." (PMID 38867002, 2024). "The relationship between the expression levels of CD274, TIGIT, PDCD1, CTLA4 and LAG3 in tumor tissues of normal and LUAD patients and the relationship between each gene and the survival rate of LUAD patients." (PMID 36959799, 2023). "This normal process is disrupted when overexpression of TIGIT outcompetes DNAM-1 for its binding to CD155, limiting NK and T lymphocytes cytotoxic activities against tumor cells." (PMID 37345111, 2023). "Given the high level of PD-1 and TIGIT expression on T cells within TIL, it became important to determine the profile of ligand expression on tumor, hemopoietic, and stromal cells." (PMID 36689623, 2023). "Vibostolimab (MK-7684) is a humanized immunoglobulin G1 mAb that binds to TIGIT and blocks its interaction with its ligands CD112 and CD155, thereby activating T cells to help kill tumor cells." (PMID 37670328, 2023). "An increasing number of studies have showed that various immune checkpoint receptors, such as PD-1, CTLA4, TIGIT, TIM3, LAG3, and inflammatory factors, are expressed and altered in the tumor microenvironment." (PMID 38110467, 2023). "Our research in NSCLC showed that anti-tumor function of CD36+CD8+ T cells was impaired, with less production of GZMB and INF-γ and higher expression of PD-1 and TIGIT." (PMID 37085798, 2023). "Following DT treatment, a decline in tumor control correlated with the depletion of PD-1+IRF4.GFP+, Tim-3+IRF4.GFP+, and TIGIT+IRF4.GFP+ CD8+ TILs, indicating that these markers denote activated and functional TILs in this context." (PMID 38178902, 2023). "For instance, the co-blockade of PD-1 and TIGIT has been shown to enhance T cell responses in preclinical models of GBM, leading to reduced tumor growth and improved survival." (PMID 37987252, 2023). "DNAM-1LO CD8+ T cells accumulate at the tumour site and upon interaction with cognate antigen exhibit an exhausted phenotype, expressing high levels of PD-1, LAG-3, TIM-3, and TIGIT." (PMID 37325585, 2023). "Usually, exhaustion of tumor-specific CD8+ T cells leads to impairment of cytokine secretion and proliferation capacity, accompanied by PD1, TIM3, LAG3 and TIGIT overexpression." (PMID 37287907, 2023). "Increasing evidence reveals a tumor cell-intrinsic expression of immune receptors, including the CD28 family member CTLA-4 as well as other checkpoint receptors like LAG3, TIGIT, and PD-1 in various malignancies." (PMID 37259155, 2023).
tumor (continued). "In TME, FZP promoted tumor cell apoptosis, increased tumor-infiltrating CD8+ T cells, and significantly inhibited the inhibitory receptors PD-1, Tim-3, and TIGIT on the membrane." (PMID 37397393, 2023). "Tregs are well-recognised suppressors of anti-tumour effector T cell responses; CD4+ CD25+ FoxP3+ TIGIT+ Tregs were significantly elevated in the bronchoalveolar lavage fluid and peripheral blood of NSCLC patients compared to healthy control subjects." (PMID 37325585, 2023). "Interactions between TIGIT and several ligands, including NECTIN3, have been shown to suppress anti-tumour immune responses through several mechanisms." (PMID 37244912, 2023). "In mice as well as in humans, TIGIT and PD-1 are co-expressed on tumor antigen-specific CD8 T cells and CD8 tumor-infiltrating lymphocytes (TILs) in cancer." (PMID 37214445, 2023). "To investigate the immune profiles of c-Scorehi tumors across the 25 TCGA tumor types, we evaluated immunomodulatory genes involved in immune checkpoint blockade response, (CD274 [PD-L1], PDCD1 [PD-1], HAVCR2 [TIM3], LAG3, TIGIT, CTLA4, and FASLG)." (PMID 37558751, 2023). "Combining regimens, with inhibitors of TIGIT and PD-1 plus CD40 agonism, in preclinical models exhibited encouraging tumor suppression." (PMID 37727377, 2023). "In some clinical cancer patients, PD-1 is co-expressed in tumor-infiltrating CD8+T cells, and the combined blockade of TIGIT and the barrier in the PD-1/PD-L1 interactions can greatly enhance cytotoxic effect of CD8+T cells." (PMID 37106742, 2023). "In THCA tumor, CTLA4 (rho = 0.691), HAVCR2 (rho = 0.610), TIGIT (rho = 0.641), VTCN1 (rho = 0.618) showed remarkably positive with FAP expression." (PMID 37166418, 2023). "The efficacy of anti-TIGIT antibodies was dependent on NK cells and NK cells were shown to regulate CD8 T cell anti-tumor immunity, including preventing their exhaustion and helping with memory formation." (PMID 37345049, 2023). "In this study, based on previous studies, we confirmed that blocking TIGIT on the surface of CAR-T cells effectively increased cytokine release in CAR-T cells and enhanced the killing of target tumor cells." (PMID 37359558, 2023). "In tumor-immune interactions, the antitumor outcome is guided by various paired stimulatory and inhibitory receptor families (including PD: PD-L1, CD155: TIGIT, CD80: CTLA4, etc.)." (PMID 37838774, 2023). "Notably, single-cell sequencing results demonstrated that tumor-associated macrophages (TAM) significantly inhibited tumor T-cell infiltration, and T cell immunoreceptor with Ig and ITIM domains–nectin cell adhesion molecule 2 (TIGIT–NECTIN2) interaction regulated the immunosuppressive environment." (PMID 36936956, 2023). "TIGIT has two ligands, CD155 (PVR) and CD112 (PVRL2, nectin-2), which are expressed by antigen-presenting cells and tumor cells in TME to decrease the activity of T cells and NK cells." (PMID 37129788, 2023). "Immunohistochemical staining targeted various T-cell markers (CD3, CD4, CD8, and FOXP3), T-cell exhaustion markers (TOX and TIGIT), a B-cell marker (CD20), and a neutrophil marker (CD66b) in tumor and tumor-free mucosa from both groups." (PMID 37835436, 2023). "Altogether, these clinical trials suggest that the TIGIT/DNAM-1 axis is indeed a target for the upcoming generation of ICIs, and a new therapeutic opportunity for the treatment of several tumor types, potentially including HCC." (PMID 36672396, 2023). "The infiltration of CD4 and CD8 T cells, as well as the levels of the TEX marker genes (HAVCR2, TIGIT, CTLA4, LAG3, and PD1) and tumor stem cell marker genes (CD44 and PROM1), were all greater in tissue samples with high TEXSRGs-score." (PMID 37957420, 2023). "Results obtained from single and multiplex immunohistochemical staining revealed significantly lower levels of immune cell infiltration and expression of PD1, TIM3, TIGIT, LAG3, and CTLA4 in liver metastases compared to the primary tumor." (PMID 37828574, 2023).
tumor (continued). "There are three ligands of TIGIT, CD155, CD112, and CD113, which are expressed on tumor cells and APCs." (PMID 37182149, 2023). "TIGIT blockade was first observed in a study that showed that deletion of the TIGIT gene in mice significantly enhanced the cytotoxic effects of NK cells and CD8+ T cells against tumor cells." (PMID 37670328, 2023). "RT plus anti-TIGIT combination therapy increased the number of CD8 + T cells and the percentage of IFNγ + TNFα + CD8 + T cells in tumor tissues and TdLNs in WT mice." (PMID 35794399, 2023). "A significant gradual increase in terms of PD1, TIGIT, and CTLA-4 expression, as evaluated singularly or in co-expression, was observed with the transition to NT and tumor site." (PMID 37898752, 2023). "OAd-SIRPα-Fc treatment conferred better antitumor activity than OAd-Siglec10-Fc and OAd-TIGIT-Fc in the MC38 model, but OAd-Siglec10-Fc showed satisfactory tumor suppression in the 4T1 model." (PMID 38016957, 2023). "Taken together, these data suggest TIGIT and CD226 co-expression is rare on immune cells within the tumour microenvironment and that CD155 is abundant on mAPCs for TIGIT-expressing T and NK cells to engage." (PMID 37596248, 2023). "RNA-seq analysis demonstrated that tumor cells recapitulate hallmarks of MCL-LN (proliferation, NF-kB and BCR), with T cells exhibiting an exhaustion profile (PD1, TIM-3 and TIGIT)." (PMID 37031299, 2023). "Based on TCGA HNSCC tumor bulk dataset, patients with HNSCC had higher TIGIT, LAG3, and CD276 expression levels than healthy individuals." (PMID 38096229, 2023). "TIGIT is a co-inhibitory receptor that interacts with its ligands, CD155 (poliovirus receptor) and CD112 (nectin-2), which are expressed on APCs and some tumor cells." (PMID 37345057, 2023). "Expression of TIGIT and TIM-3 on trNK cells, and all immune checkpoint receptors analyzed on CD8+ TRM and CD4+ TRM cells increased toward the tumor center." (PMID 37448786, 2023). "We found that CAC exhibited a significantly enriched presence of TIGIT and TOX compared to corresponding tumor-free or even inflamed mucosa." (PMID 37835436, 2023). "IL-15 can up-regulate TIGIT and CD226 via tumor-infiltrating NK cells, increasing NK cell-mediated cytotoxicity and reducing tumor metastases." (PMID 37494663, 2023). "In particular, the inhibitory checkpoint receptors TIGIT and CD96 are up-regulated during tumor progression and are able to compete with DNAM-1 for ligand binding." (PMID 37760586, 2023). "We then investigated the effects of ADCC mediated by DB against GD2-positive NB cells on the expression of CD226, TIGIT and PD-1 by NK cells, and on the expression of CD112, CD155 and PD-L1 by tumor cells." (PMID 37444427, 2023). "We also observed a higher frequency of tumor-infiltrating CD8 + T cells expressing TNF-α and IFN-γ in the combination treatment group than in the individual anti-TIGIT or RT groups." (PMID 35794399, 2023). "These mAbs target co-inhibitory ICPs like TIGIT and CD39 or co-stimulatory ICPs like OX40, 4-1BB, and ICOS, all thought to be mainly expressed by anti-tumor effector T-cells." (PMID 38057799, 2023). "CD155 on tumor cells normally interacts with CD266 expressed by NK and T lymphocytes, but this binding is disrupted due to the higher affinity of CD155 for TIGIT." (PMID 37345111, 2023). "The greatest co-expression of TIGIT and CD226 was observed within a small portion of c8, which was more abundant in the blood than the tumour (dashed line on top row)." (PMID 37596248, 2023). "TIGIT is expressed on some NK cells and can interact with its ligands CD155 and CD112, which are expressed on many tumor cells." (PMID 36960057, 2023). "In experiments examining the expression of TIGIT protein in human HCC, different parts of the tissue (normal, paracancer, and tumor tissue) and differentiated tumor tissues (well, moderate, and poorly differentiated tumors) were collected." (PMID 37124530, 2023).
tumor (continued). "We confirmed that TIGIT and CD155 were significantly highly expressed in tumor cells compared with adjacent normal pancreas cells." (PMID 37649613, 2023). "TIGIT on the surface of T cells acts as an immune checkpoint by binding to CD155 on the tumor cells’ surface, thereby inhibiting tumor cell killing." (PMID 37359558, 2023). "Blockade TIGIT-PVR/PVRL2 axis in an autologous setting using primary HCC cancer cells and the corresponding tumor-infiltrating lymphocytes should be further studied." (PMID 37383234, 2023). "In addition, we found changes in the expression of immune checkpoints, including PD-1 and TIGIT on cd47−/− CD8 cells in the tumor microenvironment that could impair their function and suggest crosstalk between CD47 signaling and other immune checkpoint pathways." (PMID 36768931, 2023). "Tumor cell-expressed ligands (CD155, CD112) binds to TIGIT and impact T cell- and NK-cell-mediated tumor recognition." (PMID 36810079, 2023). "We also compared the differences in expression levels of TEX marker genes (HAVCR2, TIGIT, CTLA4, LAG3, and PD1) and the putative tumor stem cell marker genes (CD44 and PROM1) between high and low TEXSRGs-score groups in clinical tumor samples using qRT-PCR." (PMID 37957420, 2023). "There are several clinical trials in progress targeting TIGIT and its receptor PVR to halt tumor progression." (PMID 37345111, 2023). "In the field of tumor immunotherapy research, the six immune checkpoints PDCD1, CD274, CTLA-4, LAG-3, TIGIT, and HAVCR2 can inhibit the proliferation, activation and effector functions of T cells, and maintain the immune homeostasis in the body." (PMID 37810780, 2023). "CD155 combines with CD226 to enhance T/NK cell-mediated cytotoxicity and promote anti-tumor immune response, but also interacts with TIGIT and CD96 to induce tumor immune escape and promote tumor progression." (PMID 37441080, 2023). "Given the high proportion of effector T cells within TIL we next used flow cytometry to assess the pattern of coexpression of checkpoint proteins PD-1, TIGIT, Tim-3, LAG-3, and CTLA-4 on T cells within the tumor microenvironment and peripheral blood." (PMID 36689623, 2023). "TIGIT, A2aR, PD-L2 and CD160 signalling dampens Th1 anti-tumour immunity and promotes a Treg phenotype, aiding cancer progression." (PMID 36790524, 2023). "TIGIT and CD155 were highly expressed in tumor tissues compared to those in adjacent normal tissues in a pairwise manner." (PMID 37649613, 2023). "In non-tumor tissues, immune score and the expression of CD28, OX40, CD137, CD27, PD1, TIGIT, and CD39 were significantly higher in patients with recurrence than those without recurrence." (PMID 37313417, 2023). "Our results showed that SEMA4D knockdown delays tumor growth and resulted in a significant decrease in PD1, LAG3, and TIM3 expression in TME, and a trend of decreased TIGIT expression." (PMID 37287907, 2023). "TIGIT, as an immune checkpoint, interacts with CD155 expressed on the surface of tumor cells thereby inhibiting the CD8+ T cells cytotoxicity in the TME." (PMID 37359558, 2023). "CD137 is also a costimulatory molecule expressed on activated T-cells within tumours, along with the immune checkpoints LAG3, TIM3 and TIGIT." (PMID 37013636, 2023). "The humanized antibody tiragolumab targeting T-cell immunoreceptor with Ig and ITIM domains, TIGIT is an immune checkpoint inhibitor that blocks the binding of TIGIT to its ligand CD155, thereby enhancing T-cell and NK-cell anti-tumor activity." (PMID 37046702, 2023). "Paradoxically, a recent study demonstrated that TIGIT was expressed on 53% and 28% of CD8+ and CD4+ T cells, respectively, within PDAC tumor-infiltrating lymphocyte populations." (PMID 37649613, 2023). "This review also examines emerging targets such as TIGIT and LAG3, the potential of antibodies in modulating the myeloid compartment, and tumor-specific targets for monoclonal antibody therapy." (PMID 37987252, 2023).